LGI1 (leucine rich glioma inactivated 1)
Diseases named in the same sentence as LGI1 in open-access papers (continued):
Sharing a sentence is not in itself a finding about the gene and the disease.
encephalitis (continued). "An asymmetric 18F-FDG metabolic pattern exists in patients with anti-LGI1 encephalitis." (PMID 37064193, 2023). "Moreover, pyrosequencing analysis of has-miR-2467-5p demonstrated hypomethylated status in its promoter in LGI1 encephalitis patients comparable to HDs." (PMID 37644514, 2023). "Consequently, we attempted to unravel DNA methylation changes in LGI1 encephalitis by high-throughput next-generation sequencing (NGS) for analyzing the DNA methylome and identifying methylation driver events on a genome-wide scale." (PMID 37644514, 2023). "The results were in accordance with previous studies in adult anti-LGI1 encephalitis." (PMID 37179544, 2023). "- Sodium channel blockers may be considered the preferred drug type for seizure control in anti-LGI1 encephalitis, but patients with anti-LGI1 activity are prone to adverse reactions when using ASMs." (PMID 37034075, 2023). "We have to acknowledge the difficulties in early identifying and diagnosing limbic encephalitis including anti-LGI1 encephalitis in children, due to the complexity and diversity of clinical manifestations and the atypia and dynamic change of related testing results." (PMID 37179544, 2023). "Intriguingly, LGI1 encephalitis may involve the basal ganglia and temporal lobes in an associated or isolated fashion." (PMID 37033571, 2023). "Cumulative clinical data of 19 cases of children with anti-LGI1 encephalitis." (PMID 37179544, 2023). "The rarity of anti-LGI1 encephalitis in pediatric patients may be related to a lower expression of LGI1 protein in younger individuals as observed in mice." (PMID 37391712, 2023). "However, PDCD1 without methylation changes in promoter was significantly lower in PBMCs of LGI1 encephalitis patients compared with HDs." (PMID 37644514, 2023). "Furthermore, in our previous study, we showed that increased metabolism in the basal ganglia and the hippocampus associated with decreased cortical metabolism was a general metabolic alteration observed in patients with anti-LGI1 encephalitis." (PMID 37064193, 2023). "Patient characteristics of 19 cases of children with anti-LGI1 encephalitis." (PMID 37179544, 2023). "In this report, we describe a patient who developed a rare symptom of nose aches possibly as one of symptoms of anti-LGI1 encephalitis, which highlights the possibility of atypical symptoms in children that may be misdiagnosed." (PMID 37391712, 2023). "Hyponatremia, an emblematic feature of anti-LGI1 encephalitis, was initially observed." (PMID 37275973, 2023). "Most anti-LGI1 encephalitis patients harbor autoantibodies of the IgG4 subclass, although IgG1 autoantibodies may also be present." (PMID 38201219, 2023). "With a corrected diagnosis of anti-LGI1-encephalitis, the boy was treated with intravenous immunoglobulin with a total dose of 2 g/kg over 4 days and intravenous methylprednisolone with a regimen of 15 mg/kg/d for 3 days with a four-day interval and 3 consecutive rounds in total." (PMID 37179544, 2023). "The annual incidence of anti-LGI1 encephalitis is estimated to be 0.83–2 per million persons." (PMID 40217477, 2023). "In addition, LGI1 encephalitis patients with brain MRI abnormalities presented the elevated level of PDL2 and CCL2 but lower levels of TNFα (all p < 0.05) in serum." (PMID 37644514, 2023). "To study the role of anti-LGI1 autoantibodies in the genesis of seizures, we performed acute and chronic injections of CSF and purified serum IgG of anti-LGI1 encephalitis patients in rodents, targeting the two main brain regions affected by the disease, the hippocampus and primary motor cortex." (PMID 36849262, 2023). "In addition, hypermetabolism in the basal ganglia has been shown to be most prominent in patients with FBDS; which is characteristic of anti-LGI1 encephalitis." (PMID 37064193, 2023). "Similarly, IFN-γ displayed dramatically increased expression in PBMCs of LGI1 encephalitis patients but remained unchangeable in promoter methylation status." (PMID 37644514, 2023).
encephalitis (continued). "LGI1 encephalitis patients present quite frequently with seizures." (PMID 38035091, 2023). "As for anti-LGI1 encephalitis, increased metabolism in the hippocampus, basal ganglia, and medial temporal lobe has been reported to be associated with hypometabolism within cortical areas, such as the parietal, frontal, and occipital lobes, the cingulate cortex, and the paracentral lobule." (PMID 37064193, 2023). "A general glucose metabolism pattern is observed in patients with anti-leucine-rich glioma-inactivated 1 (LGI1) antibody encephalitis; however, it is unclear whether further subregional metabolic differences exist." (PMID 37064193, 2023). "Identifying the metabolic abnormalities in these brain regions might provide new clues for understanding and interpreting the clinical presentation of patients with anti-LGI1 encephalitis." (PMID 37064193, 2023). "For LGI1 encephalitis patients (n = 6) and HDs (n = 4), miR-2467-5p expression in PBMCs was negatively associated with the serum levels of PDCD1 (r = −0.867, p = 0.002) and CSF3 (r = −0.721, p = 0.023), but favorably correlated with the serum level of CCL15 (r = 0.746, p = 0.017)." (PMID 37644514, 2023). "Binding of antibodies to LGI1 in these varied regions may lead to the complex clinical phenotypes observed in patients with anti-LGI1 encephalitis." (PMID 37264220, 2023). "RRBS was performed to study DNA methylation abnormalities in LGI1 encephalitis." (PMID 37644514, 2023). "LGI1 encephalitis may present with simultaneous distinct patterns of movement disorders depending on the cortical and subcortical structures involved in the disease." (PMID 37033571, 2023). "In a feline in vivo model of anti-LGI1 encephalitis, breakdown of tight junctions in the blood–brain barrier (BBB) was observed, specifically in the limbic regions, the areas of the brain with the highest concentration of LGI1 and thus predominantly affected by LGI1 autoantibodies." (PMID 38201219, 2023). "Then, bioinformatics algorithms uncovered the probable miR-2467-5p binding sites in the 3'untranslated region (UTR) of CSF3' and PDCD1' mRNA, and a negative correlation was found between PDCD1 expression and CCL15 expression in the serum of LGI1 encephalitis patients (r = −0.546, p = 0.013)." (PMID 37644514, 2023). "Based on this information, the patient was diagnosed with anti-LGI1 encephalitis and treated with methylprednisolone of 1000mg for 3 days, with a decrement by half every 3 days, By the 4th day of immunotherapy, the weakness had disappeared and only reoccurred seven times during her hospitalization." (PMID 37304289, 2023). "While the association of weakness with FBDS remains unclear, paroxysmal unilateral limb weakness has been identified as an initial symptom of anti-LGI1 encephalitis." (PMID 37304289, 2023). "In addition to the general cerebral lobe regions, some brain substructures, such as the cingulate gyrus, sensorimotor cortex, precuneus, and primary visual cortex, were shown to be affected by hypometabolism in the present anti-LGI1 encephalitis sample." (PMID 37064193, 2023). "Additionally, we conducted an analysis to summarize the clinical features of previously reported cases of pediatric anti-LGI1 encephalitis." (PMID 37391712, 2023). "Early treatment of anti-LGI1 encephalitis is crucial for overall prognosis and may delay the development of dementia in some cases." (PMID 37275973, 2023). "Notably, 96.4% (27/28) of patients with anti-LGI1 encephalitis in our cohort were males, which is higher than the 60–70% reported in other studies." (PMID 38152405, 2023). "Comparing with adult-onset anti-LGI1 encephalitis, which existing a pathognomonic manifestation like FBDS, pediatric anti-LGI1 encephalitis is infrequently reported and shows little similarities in clinical manifestations except typical symptoms associated with limbic encephalitis." (PMID 37179544, 2023).
encephalitis (continued). "However, an NGS-based methylation examination of LGI1 encephalitis, particularly including these cytokines/chemokines and ICMs, has not yet been reported." (PMID 37644514, 2023). "Besides, one anti-LGI1-Ab-positive encephalitis patient was positive for the antibody in serum and CSF (100%)." (PMID 37153594, 2023). "Overall, we report three childhood onset cases of anti-LGI1 encephalitis with initiating symptom of seizures, and the characteristics of clinical manifestation, course of evolution, imaging manifestation and treatment outcomes are summarized, with a review of literature." (PMID 37179544, 2023). "Thus, the weight and height of the remaining 63 patients with LGI1 antibody encephalitis were used for statistical analysis." (PMID 37592180, 2023). "Sodium channel blockers may be the best option for seizures in anti-leucine-rich-glioma-inactivated-1 (anti-LGI1) encephalitis, but patients with anti-LGI1 encephalitis are prone to side effects when using ASMs." (PMID 37034075, 2023). "Some studies suggest that when the antibody titer in the cerebrospinal fluid is less than 1:10, it may be falsely positive and anti-LGI1 encephalitis cannot be diagnosed." (PMID 37304289, 2023). "In this report, we describe five cases of anti-LGI1 encephalitis with paroxysmal limb weakness." (PMID 37304289, 2023). "Decreased PDCD1 with increased ICAM1 could predict unfavorable prognosis in one-year follow-up for LGI1 encephalitis patients." (PMID 37644514, 2023). "In addition to the asymmetric metabolic pattern of cortical regions in anti-LGI1 encephalitis, we further compared the metabolic activity within single brain regions between hemispheres." (PMID 37064193, 2023). "Using the circular binary segmentation approach, we were able to identify 77.15% of DMRs with hypo-methylated status in our RRBS data, which could help us understand the role of DNA methylation in LGI1 encephalitis." (PMID 37644514, 2023). "The general relapse rate of anti-NMDAR, anti-GABABR and anti-LGI1 encephalitis was 26%." (PMID 35757705, 2022). "The PET image of the patient with anti-LGI1 encephalitis is actually the compound of multiple different patterns of PET signals resulting from different sources, such as metabolic abnormality related to anti-LGI1 encephalitis, other brain activities, noise, and background." (PMID 35711267, 2022). "Anti-LGI1 (leucine-rich, glioma-inactivated 1) encephalitis, for example, frequently presents with normal Cerebrospinal fluid (CSF) findings: cell and protein counts may be unremarkable in up 75% of patients." (PMID 35976312, 2022). "Moreover, hyponatremia (e.g., due to carbamazepine or oxcarbazepine), cutaneous rash (e.g., due carbamazepine, phenytoin, or lamotrigine) and neurological side effects should be considered in the choice of ASM, especially in the case of anti-LGI1 encephalitis." (PMID 36672553, 2022). "More importantly, this study suggested that the patterns of PET signal changes caused by metabolic abnormalities associated with anti-LGI1 encephalitis were similar in CD patients and non-CD patients." (PMID 35711267, 2022). "Interestingly, anti-LGI1 encephalitis patients who presented with only FBDS at admission (n = 6) had significantly lower CSF CHI3L1 levels than those without FBDS symptoms (n = 24, p = 0.029)." (PMID 36685530, 2022). "CHI3L1 level in CSF is correlated with the severity and prognosis of anti-LGI1 encephalitis." (PMID 36685530, 2022). "Thus, while in NMDAR encephalitis patients, alpha diversity was reported to be higher or similar to controls, in anti-LGI1 encephalitis, it was found to be lower." (PMID 35877424, 2022). "In patients with anti-LGI1 encephalitis, on the contrary, the PGRN in the CSF remains normal." (PMID 35937071, 2022). "Herein, we report the first case of adult patients with familial anti-LGI1 encephalitis." (PMID 35493840, 2022).
encephalitis (continued). "More than half of the patients with anti-LGI1 encephalitis experienced hyponatremia usually in the early stage, and it is easy to correct, which may be related to the abnormal secretion of antidiuretic hormone." (PMID 35126787, 2022). "These seizures are considered pathognomonic of anti-LGI1 encephalitis, and their early identification (and consequent start of immunotherapy, in particular corticosteroids) can avoid the onset of cognitive (especially memory) dysfunction characteristic of the disease." (PMID 36672553, 2022). "However, the MRI results in some patients with anti-LGI1 encephalitis were normal and positron emission tomography (PET) can increase the sensitivity to LGI1 encephalitis compared to MRI." (PMID 35711267, 2022). "As all three disorders – ICI-iE, HSV-1 encephalitis and anti-LGI1 encephalitis – are rare neurological entities, this dataset can be used as a reference in future clinical studies on ICI-induced neurotoxicity, neurological autoimmune disorders, and central nervous system infections." (PMID 36426082, 2022). "Certain seizure semiologies and EEG patterns are highly characteristic for specific autoimmune encephalitis: faciobrachial dystonic seizures—brief motor seizures lasting for 1–3 s typically affecting the limbs and face simultaneously—are highly characteristic of anti-LGI1 encephalitis." (PMID 36138865, 2022). "Thus, compared to conventional visual assessment, the MVCC method combined with ICA can reveal more potential brain regions with metabolic abnormalities related to anti-LGI1 encephalitis." (PMID 35711267, 2022). "CSF CHI3L1 levels are correlated with the severity and prognosis of anti-LGI1 encephalitis." (PMID 36685530, 2022). "All patients with anti-LGI1 encephalitis harbor LGI1 antibodies in CSF." (PMID 36591253, 2022). "In contrast, significantly decreased PET signals were observed in the right supplementary motor area, the bilateral calcarine fissure and surrounding cortex, and the lobule III of the vermis, indicating that the patients with anti-LGI1 encephalitis presented hypometabolism in these brain regions." (PMID 35711267, 2022). "However, few studies have documented serum and CSF CHI3L1 levels in patients with anti-LGI1 encephalitis." (PMID 36685530, 2022). "LGI1-encephalitis mostly occurs in middle-age and older adults." (PMID 36348436, 2022). "This study demonstrated that multivariate cross-classification combined with ICA could improve, to some degree, the detection of invisible abnormal metabolism in the PET images of patients with anti-LGI1 encephalitis." (PMID 35711267, 2022). "The risk factors for mortality in the subgroup with anti-LGI1 encephalitis were not investigated because only one patient died during the disease course." (PMID 35320933, 2022). "As for the left medial part of the superior frontal gyrus, the right postcentral gyrus, the bilateral calcarine fissure and surrounding cortex, and the lobule III of the vermis, they are rarely specifically reported by previous studies about anti-LGI1 encephalitis." (PMID 35711267, 2022). "Clinical data and laboratory findings of anti-LGI1 encephalitis patients (n=35)and controls (n=22)." (PMID 36685530, 2022). "Here, we assessed the clinical performance of a commercial and an in house indirect immunofluorescent cell based assays (IIF-CBA) using paired serum/CSF of 70 patients with suspected anti-LGI1 encephalitis and positive rat brain indirect immunohistochemistry (IIHC)." (PMID 36591253, 2022). "The coexistence of anti-LGI1 and anti-mGluR5 encephalitis has been rarely reported." (PMID 36316880, 2022). "Based on this case, unilateral hyperhidrosis of the body and arm as a rare neurological presentation can be added to the phenotypic spectrum of anti-LGI1 encephalitis, and early recognition of this manifestation might support timely diagnosis and treatment." (PMID 36211373, 2022).
encephalitis (continued). "Previous reports have suggested that the type of test and patient’s sample (serum or CSF) have different clinical performances, however, there are no studies comparing different diagnostic tests on paired serum/CSF samples of patients with anti-LGI1 encephalitis." (PMID 36591253, 2022). "A recent Mayo Clinic study have reported that more than half of patients with anti-LGI1 encephalitis presented with FBDS." (PMID 36685530, 2022). "Thus, we investigated the changes in serum and CSF CHI3L1 levels in anti-LGI1 encephalitis patients and their relationship with severity and prognosis." (PMID 36685530, 2022). "Among the patients with anti-LGI1 encephalitis, no factor was found to be associated with an increased risk of acute symptomatic seizures." (PMID 35281052, 2022). "And relapses occurred in about 14 - 35% of anti-LGI1 encephalitis." (PMID 35757705, 2022). "A relatively understudied common denominator might be antibody-mediated mitochondrial dysfunction and apoptotic cell death in IgG4-AID, which so far have been implicated in PV, membranous nephropathy/IgG4-related disease and anti-LGI1 encephalitis." (PMID 35401530, 2022). "Next, we evaluated whether CHI3L1 levels could be used to identify anti-LGI1 encephalitis patients using ROC curves." (PMID 36685530, 2022). "Moreover, CSF CHI3L1 levels were higher in anti-LGI1 encephalitis patients presenting with cognitive impairment than those without cognitive impairment symptoms." (PMID 36685530, 2022). "As shown in case 1, hyponatremia is often present in anti-LGI-1 encephalitis." (PMID 36348436, 2022). "Anti-LGI1 encephalitis patients have elevated neurofilament light chain protein, glial fibrillary acidic protein and chemokine ligand 13 levels and reduced Visinin-like protein 1, Synaptosomal Associated Protein-25 (SNAP-25) and neurogranin levels in the serumand CSF." (PMID 36685530, 2022). "Moreover, the observation that all patients with anti-LGI1 encephalitis have antibodies in CSF is in line with the concept that these antibodies are pathogenic." (PMID 36591253, 2022). "As the clinical findings were consistent, the diagnosis of anti-LGI1 encephalitis was made." (PMID 35448972, 2022). "The training cohort included 17 healthy participants and 17 patients with anti-LGI1 encephalitis whose metabolic abnormality was able to be visibly detected in both the medial temporal lobe and the basal ganglia in their PET images [completely detectable (CD) patients]." (PMID 35711267, 2022). "Therefore, we strongly recommend early administration of rituximab in the management of anti-LGI-1 encephalitis, although more controlled trials are needed to corroborate this recommendation." (PMID 36348436, 2022). "Importantly, 10% of the patients with anti-LGI1 encephalitis appear to have normal MRI and CSF studies, which makes this subtype especially challenging and necessary to incorporate into differential diagnosis of suspected neurodegenerative dementias." (PMID 35046526, 2022). "The diagnosis of LGI1 encephalitis is based on LGI1 antibody detection in serum and CSF." (PMID 35453524, 2022). "In addition to the medial temporal lobe and the basal ganglia, other brain regions of patients with anti-LGI1 encephalitis were also revealed to present different PET signals from those of the healthy participants." (PMID 35711267, 2022). "This is because the prevalence and incidence of anti-LGI1 encephalitis are relatively low." (PMID 35711267, 2022). "Anti-LGI-1 encephalitis usually responds well to the first line of treatment with steroids." (PMID 36348436, 2022). "The existing studies using PET have reported that metabolic abnormalities were observed in these lobes of the patients with anti-LGI1 encephalitis, for example, the bilateral frontal lobe, the bilateral and right parietal lobe, the occipital lobe and the cerebellum." (PMID 35711267, 2022).